IL2 (interleukin 2)
Diseases named in the same sentence as IL2 in open-access papers (continued):
Sharing a sentence is not in itself a finding about the gene and the disease.
breast carcinoma (continued). "Herein, we present a case of hormone receptor negative, HER2 positive cutaneous breast cancer metastasis treated with intralesional IL-2 and topical imiquimod, which was well tolerated with only minor low grade side effects." (PMID 35712509, 2022). "Their study demonstrated that the addition of IL-21 significantly increased strong cytotoxicity against trastuzumab-resistant breast cancer cells with the synthesis and secretion of IFN-γ and IL-2, after combining HER2-targeted CAR-T cells with trastuzumab-resistant HCC1954 and BT474 cells." (PMID 35935930, 2022). "Tumor infiltration, predominantly by Tregs, was associated previously with unfavorable histologic features and poor survival outcomes in breast cancer, mainly through transforming growth factor (TGF-β) and IL-2 stimuli promoting an immunosuppressive microenvironment." (PMID 34944876, 2021). "Gene-set enrichment analysis has shown that important pathways are upregulated in response to SK1 knockdown in prostate and breast cancer cells, like KRAS, IL2/STAT5, EMT and TNF/NFκB, indicating that switching off one pathway is insufficient to completely block cancer cell growth." (PMID 34043703, 2021). "In breast cancer, IL-15 provoked higher proliferation and IFNγ production of tumor-infiltrating CD8+ T cells than IL-2, and these strong but short-lived response could be diminished by the subsequently upregulated TIM-3." (PMID 33266177, 2020). "Cytokine release assays were performed to quantify relative amounts of Tc1 (IFN-γ and IL-2) and Tc2 (IL-4) cytokines secreted in co-cultured systems containing T cells (transduced or non-transduced) and breast cancer cells (TNBC and non-TNBC)." (PMID 31804974, 2019). "Remarkably, the level of IL-2 was non-significantly increased in blood plasma of breast cancer patients, but not in AML patients, including those with primary and metastatic breast tumors." (PMID 31354733, 2019). "Apoptosis was further potentiated by the presence of interleukin (IL)-2, often included in cytotoxicity assays; however, exogenous interleukin-2 (IL-2) did not contribute significantly to γδTc cytotoxicity against breast cancer cell lines." (PMID 28713391, 2017). "Nonetheless, low-dose IL-2 is currently included in a number of clinical trials to support cellular adoptive approaches with combined infusions of NK cells and trastuzumab in HER2+ breast cancer patients (NCT02030561, NCT02843126)." (PMID 29181007, 2017). "NK-92MI cells are not dependent on IL-2, and they have been shown to have an antitumor effect on breast cancer cells in vivo." (PMID 28785259, 2017). "It was found that B7-H3Bi-armed ATC secreted more IFN-γ, TNF-α and IL-2 than unarmed ATC, and had enhanced cytotoxic activity against a wide range of human cancer cells, including lung cancer, breast cancer, colorectal cancer, pancreatic cancer, cervix cancer, prostate cancer, and glioblastoma." (PMID 27121051, 2016). "Allogeneic NK cells combined with 2 weeks’ adjuvant IL-2 were administered in a phase II trial in 20 patients with solid tumors (14 ovarian, 6 breast cancer) following the low dose, non-myeloablative preparative regimen." (PMID 25972872, 2015). "The current study also showed that NK92-MI have anti-tumor activity to a breast cancer cell line in vitro and in vivo without IL-2 supplementation." (PMID 23940545, 2013). "Upon PMA stimulation, the percentage of T lymphocytes expressing IL-4 was significantly higher in breast cancer patients than in controls (2.36 ± 0.49 vs 1.37 ± 0.16%, P=0.039), while the percentages of CD3+ cells expressing either IL-2 or IFN-γ were slightly decreased in cancer patients." (PMID 14562018, 2003).
breast carcinoma (continued). "Moreover, patients with metastatic HER2 + breast cancer and a good prognosis exhibited a higher proportion of CD4 + IL-2 + T cells relative to CD4 + IL-4 + T cells, along with an increased percentage of CD56bright NK cells, in their peripheral blood compared to patients with a poor prognosis." (PMID 41582199, 2026). "When observing the cytokine profiles of dogs with and without metastasis, IL-2 was increased in the “mammary carcinoma” group, irrespective of the metastasis status, while only dogs without metastasis in the “mammary carcinoma in the benign mixed tumor” group displayed an increase in this cytokine." (PMID 41150099, 2025). "The intraperitoneal injection of IL-31 in a murine breast cancer model resulted in CD8+ T-cell infiltration, which led to an immune response against tumor cells; better survival was also demonstrated due to the modulation of the release of cytokines like IL-10 and IL-2." (PMID 40305195, 2025). "NKG2D CAR-T cells with CD27 or 4-1BB costimulatory signaling molecules could promote the expansion and self-enrichment of CAR-T cells without the presence of IL-2, effectively enhancing the ability to recognize and eliminate breast cancer." (PMID 35935930, 2022). "In addition, the cytolytic function of CAR MUC1 T cells was evaluated in primary breast cancer, in which both CAR MUC1 constructs demonstrated a specific antitumor activity and increased interferon gamma and IL-2 secretion after coculturing with MUC1+ primary cells." (PMID 36457849, 2022). "Radiation in combination with immunostimulatory molecules such as Interleukin-2 (IL2), Toll-like receptor (TL-R) ligands and FMS-like tyrosine-kinase 3 (Flt-3) ligand have been used pre-clinically to engender the abscopal effect in mouse models of breast cancer." (PMID 29644338, 2018). "In an earlier study, we showed that in women with metastatic breast cancer low dose IL-2, low dose GM-CSF, and eight Her2Bi armed ATC infusions induced cytotoxic T cell activity directed at SK-BR-3 breast cancer cell targets that could be detected up to 4 months or more after immunotherapy." (PMID 25802762, 2015). "Although follow-up Phase II studies demonstrated that daily low dose (1.75 × 106 IU/m2/day) subcutaneous IL-2 was better tolerated in relapsed non-Hodgkin’s lymphoma and breast cancer patients and expanded cytotoxic T cells, no improvement in patient outcomes was reported." (PMID 25972872, 2015). "For example, breast cancer patients with elevated levels of COX2 and PGE2 within the tumor and the circulation presented T cells with decreased proliferation in response to CD3 antibody stimulation, reduced levels of TNF-α, interleukin (IL)-12, IL-2, and increased levels of IL-10 and IL-4." (PMID 23029485, 2012). "However, regardless of whether PR was positive or negative, the expression of IL-2 and IL-17 did not influence the survival of patients with breast cancer in this subgroup analysis." (PMID 35493488, 2022). "In another phase II study, 42 BC patients were vaccinated with a multi-antigen vaccine, which included autologous and allogeneic breast cancer cells, three TAAs (CA15-3, CEA, and CA125), and low doses of GM-CSF and IL-2." (PMID 35804943, 2022). "CD4+ T cells collected after 12 days of culture (T12) were restimulated polyclonally without exogenous IL-2 for the next 3 days in the presence or without (T15M and T15, respectively) MDA-MB-231 breast cancer cell line expressing PD-L1." (PMID 34439305, 2021). "In addition, doxorubicin co-administered with cisplatin (the latter not used in our study) upregulates PD-L1 expression in breast cancer and PD-L1 inhibition in combination with IL-2 has synergistic effects on CD8+ T cells, suggesting that these two therapies may activate converging pathways." (PMID 33344239, 2020).
breast carcinoma (continued). "In-situ studies of TIL in breast cancers demonstrate expression of the early activation markers CD38, 43 and 69, but show little or no expression of IL-2 receptor or IL-2 protein, suggesting anergic, tolerant T-cells." (PMID 11870535, 2002). "To identify factors that can induce CD177 expression on Treg cells, we purified human PB Treg cells or CD4 Tconv cells from breast cancer patients, or splenic Treg cells or CD4 Tconv from MC38 tumor-bearing mice, either non-stimulated (ns) or treated with anti-CD3/CD28 and IL-2." (PMID 34599187, 2021). "The presence of SP1 together with IL2 signaling regulators, IGFBP2, IMPDH2 and HTT in separate subnetworks that excludes RAC signaling component might indicate the presence of at least two non-redundant mechanisms in P-inter breast cancers that may determine patient outcomes." (PMID 26257336, 2015).
viral infection (228 papers, 2006 to 2026). "For example, the predicted and obtained IL-2 and IL-6 have been associated with the pathogenesis of a viral infection." (PMID 36982944, 2023). "During immune exhaustion, a gradual increase in the expression of multiple inhibitory receptors occurs and the T cells lose functions such as the production or loss of IFN-γ, TNF-α, IL-2 and compromised ability to control model chronic virus infections." (PMID 37671156, 2023). "The loss of distinct T cell functions during chronic viral infection occurs in a hierarchical manner, while IL-2 production and robust proliferation are the first functions to be lost." (PMID 35406703, 2022). "Studies have found that viral infection can cause immune organ damage by promoting the expression of IL-2, which is similar to our results." (PMID 33553290, 2020). "Reversely, Arl4d-deficient CD8 T cells show enhanced IL-2 production and maturation into effector cells during viral infection in vivo." (PMID 30382149, 2018). "IL-2 deficient mice have reduced levels of αβ T cells producing IFN-γ in response to virus infection further suggesting a key role for IL-2 in IFN-γ production." (PMID 25785862, 2015). "The relevance of measuring IFN-γ/IL-2 production profiles, as diagnostic correlate of memory T-cell responses, has been studied outside the field of Q fever, specifically in a number of viral infections, and in Mycobacterium tuberculosis infection." (PMID 25729380, 2015). "It is well established that most viral infections cause damage by an interplay of direct infection and concomitant host response, evidenced by up-regulation of cytokine production, notably TNFα, IL-2, IL-6, IL-8 and other chemicals." (PMID 24628767, 2014). "In chronic virus infections the loss of CD8 T-cell proliferative capacity is commonly associated with a progressive reduction of IL-2 production." (PMID 25255144, 2014). "Ld-IL2 treatment increased Treg cell numbers and may be associated with a lower incidence of viral infections and GVHD." (PMID 37175505, 2023). "Additionally, stimulated splenocytes derived from ARPV/ZIKV-immunized mice produced significantly more cytokines associated with viral infection than control groups at both 8 dpi and 35 dpi, with notable increases in IL-2, IFN-γ and TNF-α." (PMID 34696250, 2021). "As T cells age, they also lose their capacity to produce and respond to IL-2 and IL 12 as major inducers of Th1 type responses, resulting in increased susceptibility to bacterial and viral infections and neoplasias among elderly persons, compared to young adults." (PMID 27456231, 2016). "Similarly, the concentrations of IL-2 and IL-6 in the FA group were lower (no significance) compared with the CK and UA groups, suggesting that fermentation may have reduced the virus content, as IL-2 and IL-6 levels are associated with viral infections." (PMID 37180273, 2023). "Thus, the presence of a cytokine shift towards enhanced Th2 expression in OCI cases may have resulted in decreased serum level of IFN-γ and IL-2 cytokines associated with subsequently immune clearance of the viral infection." (PMID 26221136, 2015). "These cultured MPs are, therefore, far from being able to facilitate a functional TL profile compatible with the control of viral infection, which would involve the secretion of IFNγ, IL2 and TNFα." (PMID 40181981, 2025). "Cytokine-mediated interventions, such as IL-2 administration, represent another potential approach to induce functional Treg activation during viral infection." (PMID 40806563, 2025). "Viral diseases and other intracellular pathogens are best controlled by type 1 responses characterized by cytokines such as type 1 IFNs, IFNγ, TNFα, and IL-2 along with antibody isotypes IgG2a/c (depending on mouse strain)." (PMID 40872809, 2025).
viral infection (continued). "IL2RG has been shown to contribute to the immune response during secondary viral infections by promoting the swift entry of memory cells into the cell cycle and enabling IL-2 signal-dependent competitive proliferation." (PMID 40724541, 2025). "It is also in line with the reciprocal finding that IL-2 blockade during viral infection led to the increase in the Tfr/Tfh ratio, thus reflecting enhanced transition of CD25+ Tfr-phen cells into CD25- Tfr cells in the absence of IL-2." (PMID 40710339, 2025). "This shift allows them to sustain the production of pro-inflammatory cytokines such as interferon-gamma (IFNγ), tumor necrosis factor (TNF), and interleukin-2 (IL-2), which drive immune responses against viral infections." (PMID 40453076, 2025). "The JAK-STAT pathway was also enriched, probably due to the synthesis and release of IL2 induced by viral infection." (PMID 40474210, 2025). "Inhibition of one of them, JNK, significantly impaired viral infection in phytohemagglutinin-interleukin-2 (PHA-IL2)-activated T cells." (PMID 39599797, 2024). "This correlates with the ‘cellular response to interleukin 2’ (dermal cluster 8): interleukin 2 is a cytokine produced primarily by T cells (a mononuclear cell) and it primarily activates lymphocytes that are important during viral infections." (PMID 39215940, 2024). "Serum IL-2 has a role in anti-bacterial and anti-viral infection and in inhibiting the proliferation and differentiation of tumour cells." (PMID 38496017, 2024). "The levels of IL-2 showed a direct association with IFN-γ, indicating their potential to predict a protective response against viral infection." (PMID 39335628, 2024). "IL-2 is expressed in leukocytes, spleen, and hindgut, increasing post Edwardsiella tarda and viral infections (HIRRV)." (PMID 39684540, 2024). "As is known, IL-2 is involved in the Th1-type immune response and the immune reaction against viral infections." (PMID 39519310, 2024). "The expansion of resting memory CD8+ T cells in response to IL‐2 observed here is consistent with reported bystander activation of memory CD8+ T cells in viral infections or IL‐2 cytokine therapy." (PMID 37840018, 2024). "Accordingly, low doses of IL-2 therapies have also already been proven to display immune-boosting effects in the context of viral infections and even in pathologies related to EBV infections." (PMID 38255717, 2024). "Paracrine IL-2 signalling drives the CD8 + T cell expansion and differentiation that allow protection against viral infections, but the underlying molecular events are incompletely understood." (PMID 39261466, 2024). "We analyzed splenocytes by flow cytometry 30 d after infection because it has been shown that Tfr generation is delayed because of high levels of IL-2 present in the early stages of viral infection." (PMID 36754569, 2023). "Viral infection triggers an extensive cytokine response, such as IL-1, IL-2, IL-6, TNF-α, IFN-γ, IFN-induced protein 10 kDa and so on." (PMID 38027806, 2023). "To encapsulate, our findings point to the importance of IL-2 in the body’s fight against viral infections like H3N2 IAV." (PMID 37900310, 2023). "For example, Pb suppresses the functions of IgM-type B cells, helper T cells, TNFα, IFN-γ, and IL-2, which contribute to defense against viral infections, but enhances the functions of IL-1 and 8, which induce inflammatory responses." (PMID 37508115, 2023). "Recent work in a chronic viral infection model demonstrated that IL-2 influences the differentiation of stem-like CD8+ T cells, creating distinct sets of PD-1+CD8+ effector T cells with superior antiviral activity as compared to PD-1 blockade treatment alone." (PMID 36845705, 2023). "Defects in IFN-γ and IL-2 production with age have been shown to correlate with reduced protection from viral infection and reduced vaccine efficacy." (PMID 37386041, 2023).